SLC26A11 (solute carrier family 26 member 11)
Description:
Sodium-independent anion exchanger mediating bicarbonate, chloride, sulfate and oxalate transport (By similarity). Exhibits sodium-independent sulfate anion transporter activity that may cooperate with SLC26A2 to mediate DIDS-sensitive sulfate uptake into high endothelial venules endothelial cells (HEVEC). In the kidney, mediates chloride-bicarbonate exchange, facilitating V-ATPase-mediated acid secretion (By similarity). May function as a chloride channel, playing an important role in moderating chloride homeostasis and neuronal activity in the cerebellum (By similarity).
Tractability: Antibody: UniProt places it where antibodies can reach, with high confidence; its Gene Ontology location is reachable by antibodies, with high confidence; UniProt predicts a signal peptide or a membrane-spanning region. PROTAC: ubiquitination databases record sites on it.
Gene: Protein-coding gene on chromosome 17 (80,219,699 to 80,253,509, forward strand). Ensembl gene ENSG00000181045.
Subcellular location: Cell membrane; Lysosome membrane; Apical cell membrane; Basolateral cell membrane
Subcellular location (Human Protein Atlas): Golgi apparatus; Vesicles; Nucleoplasm
Pathways (Reactome):
Metabolism: Transport and metabolism of PAPS
Transport of small molecules: Inorganic anion exchange by SLC26 transporters
Gene Ontology:
Molecular function: monoatomic anion transmembrane transporter activity; protein binding; chloride channel activity; chloride:bicarbonate antiporter activity; sulfate transmembrane transporter activity; sulfate:proton symporter activity; secondary active sulfate transmembrane transporter activity
Biological process: sulfate transmembrane transport; chloride transmembrane transport; oxalate transport; transmembrane transport; inorganic anion transport; proton transmembrane transport
Cellular component: endoplasmic reticulum; extracellular exosome; Golgi apparatus; lysosomal membrane; membrane; plasma membrane; apical plasma membrane; basolateral plasma membrane
Genetic constraint (gnomAD): Loss-of-function variants: 59 observed, 60.68 expected, observed/expected ratio (o/e) 0.97, 90% interval 0.79 to 1.21. The upper end of that interval is the gene's LOEUF score, 1.21, which puts it in group 5 of 6, group 1 being the genes least tolerant of losing a copy. Missense variants: 790 observed, 772.37 expected, observed/expected ratio (o/e) 1.02, 90% interval 0.96 to 1.09. Synonymous variants: 411 observed, 358.69 expected, observed/expected ratio (o/e) 1.15, 90% interval 1.06 to 1.24.
Homologues: Orthologues: chimpanzee SLC26A11 (99% identical), macaque SLC26A11 (95% identical), dog SLC26A11 (89% identical), pig SLC26A11 (83% identical), guinea pig SLC26A11 (82% identical), rat Slc26a11 (81% identical), mouse Slc26a11 (81% identical), rabbit SLC26A11 (75% identical), tropical clawed frog slc26a11 (59% identical), zebrafish slc26a11 (58% identical), Drosophila melanogaster CG7912 (40% identical), Drosophila melanogaster CG5002 (39% identical), and 6 more. Paralogues in human: SLC26A6 (27% identical), SLC26A3 (27% identical), SLC26A4 (26% identical), SLC26A1 (26% identical), SLC26A5 (26% identical), SLC26A2 (24% identical), SLC26A9 (24% identical), SLC26A7 (22% identical), SLC26A8 (20% identical).
Diseases named in the same sentence as SLC26A11 in open-access papers:
SLC26A11 is named in the same sentence as 12 diseases in open-access papers, as found by Europe PMC text mining. Sharing a sentence is not in itself a finding about the gene and the disease. The quoted sentences say what the papers report.
breast carcinoma (2 papers, 2018 to 2023). "This certainly encourages further research to delineate the role of SLC26A11 in the interplay between breast cancer and diabetes." (PMID 37511575, 2023). "Despite silico-derived data being obtained from a small number of patients, we were able to identify ALDH1A3, MED20, PABPC4, SLC26A11 and SCP2 as deregulated genes in diabetic breast cancer patients, which coincided with our microarray data." (PMID 37511575, 2023).
endometrial cancer (1 paper, 2023). Primary or metastatic malignant neoplasm involving the endometrium (mucous membrane that lines the endometrial cavity). "However, according to the Human Protein Atlas, SLC26A11 gene expression is unfavorable in both liver and endometrial cancers." (PMID 37511575, 2023).
gastric cancer (1 paper, 2021). A primary or metastatic malignant neoplasm involving the stomach. "With the help of univariate cox regression analysis, we found that six lncRNAs, lnc-SLC26A11, lnc-CHAF1B-3, lnc-CHAF1B-2, LINC00106, MIR3142HG and lnc-PTPA-3 had significant correlation with prognosis in gastric cancer." (PMID 34760687, 2021). "Taken together, the immune-related lncRNA signature was established with lnc-SLC26A11, lnc-CHAF1B and lnc-PTPA attributing to its prominent prognosis predictive potential in gastric cancer." (PMID 34760687, 2021).
ischemic stroke (1 paper, 2023). A stroke disorder caused by obstruction of blood flow to the brain, due to thrombotic (local blood clot formation) or embolic (due to a blood clot or other material traveling from another site) event. "Here, we determine whether SLC26A11 is the major chloride entry pathway under hypoxia and could be the target for protection against ischemic stroke." (PMID 37380823, 2023).
Stroke (1 paper, 2023). Sudden impairment of blood flow to a part of the brain due to occlusion or rupture of an artery to the brain. "In animals receiving SLC26A11-specific siRNA, neurons close to the infarct core were negatively stained for SLC26A11, suggesting that siRNA has successfully inhibited SLC26A11 upregulation in neurons after stroke." (PMID 37380823, 2023). "In the animal stroke model, SLC26A11 upregulation was mainly located in surviving neurons close to the infarct core." (PMID 37380823, 2023). "To examine the role of SLC26A11 under pathological conditions, we created a rat model of stroke reperfusion." (PMID 37380823, 2023). "In conclusion, we have identified that SLC26A11 is important for neuronal oncosis following hypoxia and stroke." (PMID 37380823, 2023). "Both scrambled siRNA and SLC26A11 siRNA treatments, as well as vehicle application, have demonstrated improvement in neurological functions following stroke." (PMID 37380823, 2023). "At days 1 and 3 after stroke, animals receiving vehicle and scrambled siRNA exhibited a more significant drop of motor functions compared to animals receiving SLC26A11 siRNA treatment." (PMID 37380823, 2023). "The in vivo effect of blocking SLC26A11 under hypoxic conditions was further studied using a rat model of stroke reperfusion." (PMID 37380823, 2023). "Blocking SLC26A11 could achieve neuroprotection and improve functional outcome in stroke reperfusion." (PMID 37380823, 2023). "Interestingly, the expression pattern of TRPM4 in neurons after stroke is also similar as SLC26A11, mainly located within the surviving tissue close to the infarct core." (PMID 37380823, 2023). "In vivo effect of SLC26A11 was evaluated on a rat stroke reperfusion model." (PMID 37380823, 2023). "In a rat stroke reperfusion model, SLC26A11 was mainly located in surviving neurons close to the infarct core, suggesting that the hypoxic environment could induce SLC26A11 expression." (PMID 37380823, 2023). "Blocking SLC26A11 could attenuate cerebral injury after stroke reperfusion." (PMID 37380823, 2023). "Inhibition of SLC26A11 could be a novel therapeutic strategy for stroke." (PMID 37380823, 2023).
cancer (3 papers, 2016 to 2023). A tumor composed of atypical neoplastic, often pleomorphic cells that invade other tissues. "Nonetheless, it is apparent that SLC26A11 has an established link with cancer as well as altered glucose levels." (PMID 37511575, 2023). "The contribution of SLC26A11 to cancer development is exhibited when a chimeric protein forms by the fusion of RNF213 and SLC26A11 in CML." (PMID 37511575, 2023).
SLC26A11 also shares sentences with these, for which no sentence is quoted: tumor (2 papers); atherosclerosis (1); cerebrovascular disease (1); diabetes (1); infection (1); sarcoma (1).